MFAP4 (microfibril associated protein 4)
Diseases named in the same sentence as MFAP4 in open-access papers (continued):
Sharing a sentence is not in itself a finding about the gene and the disease.
cancer (20 papers, 2017 to 2025). A tumor composed of atypical neoplastic, often pleomorphic cells that invade other tissues. "Although MFAP4 has been implicated in the prognosis of various cancers, its therapeutic potential remains underexplored." (PMID 40061958, 2025). "Although it has been implicated in the progression and development of certain cancers, the exact biological function and role of MFAP4 in disease pathogenesis remains incompletely understood, suggesting the need for further studies to identify it as a potential therapeutic target." (PMID 40061958, 2025). "Microfibrillar-associated protein 4 (MFAP4) is an extracellular glycoprotein that may be involved in cell adhesion, and dysregulation of this protein is reported in a variety of malignant tumors." (PMID 39170516, 2024). "Our study brings MFAP4, a molecule with a history of context-dependent roles in cancer, into the spotlight of TNBC research." (PMID 41451212, 2025). "Significant variation in MFAP4 expression has been reported in cancer, and MFAP4 has been suggested as a potential prognostic and predictive biomarker in different types of human cancers." (PMID 35805199, 2022). "In cancer, MFAP4 seems to be differentially regulated depending on the specific cancer type and location." (PMID 35805199, 2022). "We focus particularly on the role of MFAP4 in elastic fiber formation, integrin signaling and cancer." (PMID 35805199, 2022). "All in all, existing literature reports opposing changes in MFAP4 expression in different cancer types, possibly reflecting the tissue-specific characteristics." (PMID 35805199, 2022). "MFAP4 belongs to a family of fibrinogen-related domain proteins and plays a pivotal role in various pathological conditions involving tissue remodeling, including fibrosis, cardiovascular diseases, aging, and cancer." (PMID 39822989, 2025). "Second, MFAP4 and EFEMP1 have been well studied in various cancers, and the intricate mechanisms underlying the upregulation of MFAP4 and EFEMP1 in platinum-resistant OC patients remain unclear, necessitating further exploration in future research." (PMID 39822989, 2025). "However, the exact pattern of MFAP4 regulation and its possible role in distinct cancer types appear contradictive." (PMID 35805199, 2022). "Therefore, more mechanistic studies are needed to determine the exact role of MFAP4 in cancer pathogenesis, considering the cellular and histological differences between the distinct disease states." (PMID 35805199, 2022). "Interestingly, MFAP4 upregulation in cancer is often reported in tissues of low stiffness, such as neural tissue and blood." (PMID 35805199, 2022). "MFAP4 might also serve different functions depending on its location within the cancer and the surrounding stroma." (PMID 35805199, 2022). "Interestingly, the genes C15orf48 and MFAP4 showed an inconsistently directional trend across the cancers, suggesting heterogenous signaling and tumorigenesis pathways between cancer types." (PMID 36009531, 2022). "Another glycoprotein with significant site-specific glycosylation changes was MFAP4, which has been reported to be involved in several cancers and may function as a tumor suppressor in PCa56." (PMID 34354152, 2021). "Low methylation of MFAP4 may increase secretory MFAP4, which may act as an autocrine agent by binding to the cancer cell integrin receptors, and as a paracrine agent by binding to endothelial cell integrin receptors to increase angiogenesis." (PMID 28881822, 2017). "It has been suggested that the role of MFAP4 in cancer might be dual, with MFAP4 acting as a tumor suppressor facilitating inflammatory cell recruitment and immunological surveillance in early-stage cancer, while promoting cell proliferation and migration in later, advanced stages." (PMID 35805199, 2022). "In the W2 cluster, DEGs include POSTN, MFAP4, DCN, and LUM, which are closely involved in extracellular matrix organization as well as in cancer invasiveness." (PMID 39190696, 2024).
cancer (continued). "This establishes MFAP4 not just as a downstream consequence of cancer, but as an upstream regulator." (PMID 41451212, 2025). "MFAP1, MFAP2 and MFAP3 were up-regulated in both EAC and ESCC, while MFAP4 and MFAP5 were down-regulated in cancer tissues, indicating that MFAP2 might play crucial role in ESCC." (PMID 40657371, 2025). "In contrast to MFAP2, the expression of MFAP4 and MFAP5 was downregulated in cancer tissues." (PMID 40657371, 2025).
tumor (19 papers, 2019 to 2026). "To elucidate the molecular mechanism underlying MFAP4’s tumor-suppressive effects, we leveraged transcriptome data from the TCGA-TNBC cohort." (PMID 41451212, 2025). "In addition, high levels of MFAP4 expression were associated with poorer patient prognosis and later clinical grading of the tumor." (PMID 40061958, 2025). "Low MFAP4 levels in tumor tissue or even in circulation (as MFAP4 is a secreted protein) could identify high-risk TNBC patients who may require more aggressive treatment or be candidates for PI3K/AKT inhibitors." (PMID 41451212, 2025). "This suggests that the loss of MFAP4 in the tumor microenvironment may be a permissive event that facilitates the EMT program, thereby empowering TNBC cells to migrate and invade." (PMID 41451212, 2025). "On the other hand, it may actively remodel the TME into a more anti-tumor state by recruiting beneficial immune cells, a hypothesis that aligns perfectly with the immune-hot phenotype of the MFAP4-high/low-risk group identified by our model." (PMID 41451212, 2025). "Furthermore, high MFAP4 tumor levels have been associated with increased survival." (PMID 35805199, 2022). "Our study established a TME-centric prognostic signature and, more importantly, identified MFAP4 as a novel tumor suppressor in TNBC." (PMID 41451212, 2025). "Crucially, pharmacological activation of this pathway with MHY1485 partially rescued the anti-tumor effects induced by MFAP4." (PMID 41451212, 2025). "In this study, significant correlations were found between MFAP4 levels in tumor samples and WHO grade, IDH status, 1p/19q codeletion, primary therapy outcome, age and survival." (PMID 40061958, 2025). "Collectively, these results provide strong evidence that MFAP4 functions as a tumor suppressor in TNBC by inhibiting key malignant phenotypes." (PMID 41451212, 2025). "We have identified MFAP4, a previously underexplored extracellular matrix protein, as a key tumor suppressor in TNBC." (PMID 41451212, 2025). "We identify the previously underexplored ECM protein, MFAP4, as a key tumor suppressor in TNBC that functions by restraining the PI3K/AKT/mTOR pathway, a cornerstone of TNBC malignancy." (PMID 41451212, 2025). "To further explore the role of MFAP4 in tumor immune response, we used TISIDB to calculated the correlation of MFAP4 expression with immunoinhibtors, chemokines and chemokine receptors." (PMID 40061958, 2025). "For instance, while MFAP4 acts as a tumor suppressor in lung and hepatocellular carcinoma, its high expression correlates with poor prognosis in smooth muscle sarcoma and pleomorphic adenomas." (PMID 41451212, 2025). "We subsequently elucidated the tumor-suppressive functions of MFAP4 in TNBC and, for the first time, uncovered a mechanistic axis whereby extracellular MFAP4 negatively regulates the intracellular PI3K/AKT/mTOR signaling pathway." (PMID 41451212, 2025). "The application of unbiased screening techniques, such as co-immunoprecipitation mass spectrometry using recombinant MFAP4, is crucial for the clear identification of cell surface receptors mediating MFAP4 anti-tumor signaling in TNBC cells." (PMID 41451212, 2025). "Among these five genes, the SPARCL1, EFEMP1 and MFAP4 had significant highly methylation between normal and tumor tissues using GSCA online platform." (PMID 37563710, 2023). "In prostate and urinary bladder cancers, MFAP4 level is decreased, and it was consequently suggested to exert tumor-suppressive effects." (PMID 35805199, 2022). "To corroborate these findings, we performed IHC staining on tumor sections from 6 patients from our scRNAseq cohort using MFAP4 as a marker for elastic type differentiation." (PMID 34921143, 2021). "Mechanistic studies are needed to explore how MFAP4 modulates the tumor microenvironment." (PMID 40061958, 2025). "MFAP4 expression is effective in distinguishing tumor tissue from normal brain tissue." (PMID 40061958, 2025).
tumor (continued). "This discovery provides a new layer of understanding of TME-tumor cell crosstalk and presents MFAP4 as a promising biomarker and therapeutic target.A key strength of our prognostic signature lies in its ability to reflect the underlying immune landscape of TNBC." (PMID 41451212, 2025). "Given that integrins are effective activators of the PI3K/AKT pathway, we hypothesize that in TNBC, MFAP4 may exert its tumor-suppressive effect by engaging similar integrin receptors." (PMID 41451212, 2025). "However, expression in the NAU was predicted to be driven by ALDH1A2 and MFAP4 —genes that are both notoriously downregulated in other genitourinary malignancies compared to normal samples, likely suggesting tumor-suppressive roles." (PMID 35626146, 2022). "Thus, it would be of particular interest to examine whether knockdown or inhibition of MFAP4, NPTX1, and/or HMGA2 suppresses tumor development of BAP1-deficient MMe cells." (PMID 37479714, 2023). "The high expression of MFAP4 and EFEMP1 exhibited increased stromal, immune, and ESTIMATE scores; however, they demonstrated an inverse correlation with tumor purity." (PMID 39822989, 2025). "As expected, Mfap4 knockdown did not lead to tumor development, whereas Pten knockdown triggered the transformation of the cells leading to tumor formation." (PMID 37935709, 2023). "MFAP4 was expressed in spindle cells of the tumor stroma, but not in the tumor or normal epithelial cells." (PMID 34921143, 2021). "We found that the mean methylation level of ITM2A, GALNTL1, FAM107A, and MFAP4 was significantly higher in tumor tissue while the methylation level of PGM5 was higher in normal tissue." (PMID 33376725, 2020). "Notably, MFAP4, an ECM-related gene within the signature, was identified as a key tumor suppressor." (PMID 41451212, 2025). "Additionally, a negative correlation was found between high expression of MFAP4 and EFEMP1 and tumor purity." (PMID 39822989, 2025). "Whether the expression differences were significant was further verified in the TCGA database (Normal,N = 55; Tumor,N = 701), and interestingly, only MFAP4 and COL3A1 were differentially expressed in normal and tumor patients, and the remaining genes were not significantly differentially expressed." (PMID 40061958, 2025).
infection (10 papers, 2013 to 2025). The state of being infected such as from the introduction of a foreign agent such as serum, vaccine, antigenic substance or organism. "We then transfected the CFs with si-IGFBP6, followed by infection with or without Lentiviral-Flag-MFAP4 upon TGF-β1 stimulation." (PMID 41208894, 2025).
cardiovascular disease (9 papers, 2013 to 2025). "Microfibrillar-associated protein 4 (MFAP4) is involved in fibrotic and cardiovascular diseases." (PMID 38740766, 2024). "Apart from the close association between MFAP4 and remodeling-related disorders, it was also shown that MFAP4 could also serve as a candidate biomarker for cardiovascular diseases such as HF." (PMID 38397416, 2024). "We have previously shown that microfibrillar-associated protein 4 (MFAP4) is an ECM protein with relatively high expression in the heart and arteries and that systemic MFAP4 levels vary with cardiovascular disease as well as fibrotic disease." (PMID 34805319, 2021). "The role of MFAP4 in cardiovascular diseases is still unknown, and therefore we studied serum MFAP4 in a clinical cohort to establish a link between serum MFAP4 levels and different stages of atherosclerotic CVD." (PMID 24349233, 2013). "Moreover, we aimed to evaluate the significance of MFAP4 as a marker of cardiovascular disease (CVD) and to correlate MFAP4 with other known ECM markers, such as fibulin-1, osteoprotegerin (OPG), and osteopontin (OPN)." (PMID 24349233, 2013).
renal disease (1 paper, 2024). "Further, MFAP4 levels are increased in liver and renal disease, however, in renal disease, this may be to underlying CVD." (PMID 39465398, 2024).
respiratory diseases (1 paper, 2016). "Moreover, MFAP4 has been shown to be involved in respiratory diseases." (PMID 27378383, 2016).
MFAP4 also shares sentences with these, for which no sentence is quoted: prostate carcinoma (3 papers); type B aortic dissection (3); COVID-19 (2); Obesity (2); peripheral arterial disease (2); pulmonary hypertension (2); type 1 diabetes mellitus (2); alcoholic liver diseases (1); bacterial infection (1); benign prostate hyperplasia (1); cataract (1); congenital heart disease (1); coronary artery calcification (1); craniosynostosis (1); cyst (1); genetic disorder of the (1); heart disease (1); Hepatitis (1); Hypertension (1); inflammation (1); Inguinal hernia (1); lipidosis (1); myeloma (1); non-alcoholic fatty liver disease (1); oral submucous fibrosis (1); portal hypertension (1); pulmonary disease (1); Salmonella Infections (1); serous ovarian cancer (1); ST Elevation Myocardial Infarction (1).
A further 4 diseases each share a sentence with MFAP4 in 1 paper.